CHM (CHM Rab escort protein)
Description:
Substrate-binding subunit of the Rab geranylgeranyltransferase (GGTase) complex. Binds unprenylated Rab proteins and presents the substrate peptide to the catalytic component B composed of RABGGTA and RABGGTB, and remains bound to it after the geranylgeranyl transfer reaction. The component A is thought to be regenerated by transferring its prenylated Rab back to the donor membrane. Besides, a pre-formed complex consisting of CHM and the Rab GGTase dimer (RGGT or component B) can bind to and prenylate Rab proteins; this alternative pathway is proposed to be the predominant pathway for Rab protein geranylgeranylation.
Synonyms: REP-1; TCD; DXS540; GGTA; HSD-32
Tractability: PROTAC: ubiquitination databases record sites on it; its protein half-life has been measured.
Gene: Protein-coding gene on chromosome X (85,861,180 to 86,047,561, reverse strand). Ensembl gene ENSG00000188419.
Subcellular location: Cytoplasm, cytosol
Subcellular location (Human Protein Atlas): Nucleoplasm; Cytosol
Pathways (Reactome):
Metabolism of proteins: RAB geranylgeranylation
Vesicle-mediated transport: RAB GEFs exchange GTP for GDP on RABs
Gene Ontology:
Molecular function: protein binding; small GTPase binding; Rab geranylgeranyltransferase activity; GDP-dissociation inhibitor activity
Biological process: protein geranylgeranylation; protein targeting to membrane; vesicle-mediated transport; visual perception; intracellular protein transport; small GTPase-mediated signal transduction
Cellular component: cytosol; Rab-protein geranylgeranyltransferase complex; nucleus
Gene-disease validity (ClinGen):
ClinGen rates the evidence that CHM causes each of these diseases.
choroideremia (X-linked): Definitive. Choroideremia (CHM) is an X-linked chorioretinal dystrophy characterized by progressive degeneration of the choroid, retinal pigment epithelium (RPE) and retina.
Homologues: Orthologues: chimpanzee CHM (99% identical), macaque CHM (97% identical), pig CHM (89% identical), dog CHM (88% identical), rabbit CHM (88% identical), guinea pig CHM (84% identical), mouse Chm (83% identical), rat Chm (83% identical), tropical clawed frog chm (56% identical), zebrafish chm (53% identical), Drosophila melanogaster Rep (29% identical), Caenorhabditis elegans rep-1 (26% identical). Paralogues in human: CHML (72% identical), GDI2 (18% identical), GDI1 (18% identical).
Diseases named in the same sentence as CHM in open-access papers:
CHM is named in the same sentence as 75 diseases in open-access papers, as found by Europe PMC text mining. Sharing a sentence is not in itself a finding about the gene and the disease. The quoted sentences say what the papers report.
choroideremia (123 papers, 2006 to 2025). "Choroideremia is an X‐linked recessive disease caused by mutations in the CHM gene, a member of a large class of retinal disorders." (PMID 40474765, 2025). "Choroideremia, caused by mutations in the CHM gene, is another example where AAV gene therapy has shown promising results." (PMID 40429522, 2025). "Phase III and II clinical trials of choroideremia gene therapy based on AAV2 encoding the REP1 gene [NCT03496012, NCT02671539, and NCT02407678], known in humans as CHM [NCT02341807], have also been completed." (PMID 40002778, 2025). "Choroideremia is an X-linked retinal degeneration caused by the loss of function mutations involving the CHM gene, located on chromosome Xq21.2, which encodes the 95-kDa ubiquitously expressed Rab escort protein 1 (REP1)." (PMID 37762657, 2023). "Choroideremia (CHM) is an X-linked chorioretinal dystrophy, caused by mutations in the CHM gene, encoding the ubiquitously expressed Rab escort protein 1 (REP1)." (PMID 37759997, 2023). "Another viral-based gene therapy under consideration targets choroideremia, an X-linked recessive choroidal dystrophy caused by a mutation in the CHM gene." (PMID 35467460, 2022). "Choroideremia (MIM #303100) is an X-linked recessive condition caused by pathogenic alterations in the CHM gene and characterized by the progressive degeneration of choroid, photoreceptors (PR) and retinal pigment epithelium (RPE)." (PMID 35886051, 2022). "We describe a family in which two adult females and an adult male, as well as two children, were carriers of the CHM c.1349+1G>A alteration, causing choroideremia in the adult cases." (PMID 35886051, 2022). "Background and objectives: Choroideremia (CHM) is an X-linked recessive chorioretinal dystrophy caused by mutations involving the CHM gene." (PMID 33445564, 2021). "Choroideremia is caused by mutations in the CHM gene (OMIM 303390) encoding Rab-escort protein 1 (REP1), which is involved in lipid prenylation and intracellular protein trafficking." (PMID 32467628, 2021). "Because choroideremia is caused by a single mutation or deletion of the CHM gene, gene therapy is an attractive treatment in choroideremia, and both phase II and phase III clinical trials have been actively conducted recently." (PMID 32107442, 2020). "To date, more than 280 mutations in the CHM gene have been reported to be associated with choroideremia, most of which are point mutations that directly introduce premature stop codons." (PMID 32487042, 2020). "Choroideremia is caused by mutations in the CHM gene (OMIM, 300390), which encodes the geranylgeranyl transferase Rab escort protein-1 (REP-1)." (PMID 32487042, 2020). "For each of the two families, family testing revealed the presence of the familial CHM mutation in an asymptomatic male with retinal features consistent with choroideremia." (PMID 33110609, 2020). "Another hosting miRNA gene, CHM, has been involved in an X-linked disease, choroideremia, also known as tapetochoroidal dystrophy, characterized by progressive dystrophy of the choroid, retinal pigment epithelium and retina." (PMID 32356180, 2020). "This Australian cohort now consists of 25 genetically confirmed choroideremia-affected families, with a total of 23 different CHM mutations identified." (PMID 33110609, 2020). "Six novel mutations were identified, which not only expanded the mutational spectrum of CHM gene, but also improve our understanding of choroideremia." (PMID 32487042, 2020). "In this study, seven patients with choroideremia were identified from 578 patients with a clinically suspected diagnosis of RP, and six novel variants in CHM were identified." (PMID 32487042, 2020). "A more severe phenotype was also associated with whole CHM gene deletion in a previous genotype-phenotype choroideremia study." (PMID 31963381, 2020).
choroideremia (continued). "Seven patients with choroideremia were identified, and six novel variants in CHM (c.1960 T > C p.Ter654Gln, c.1257del p.Ile420*fs1, c.1103_1121delATGGCAACACTCCATTTTT p.Tyr368Cysfs35, c.1414-2A > T, and c.1213C > T p.Gln405Ter, c.117-1G > A) were revealed." (PMID 32487042, 2020). "The choroideremia gene, CHM (OMIM #300390), encodes the REP1 protein, a 653 amino acid polypeptide essential for intracellular trafficking and post-translational prenylation of proteins within the human eye." (PMID 31548516, 2019). "Choroideremia (CHM) is an x-linked recessive chorioretinal dystrophy, with 30% caused by nonsense mutations in the CHM gene resulting in an in-frame premature termination codon (PTC)." (PMID 30689859, 2019). "Since variations in male phenotypes cannot be explained by mutations in CHM only, genetic modifiers or environmental factors must play a role in the onset and progression of degeneration in choroideremia." (PMID 31548516, 2019). "In some cases of choroideremia, deep-intronic mutations can create a cryptic splice acceptor site that results in the insertion of a pseudoexon in the CHM transcript." (PMID 31548516, 2019). "Choroideremia is a rare X-linked recessive inherited retinal disease caused by sequence variations or deletions in the CHM gene which are usually functionally null mutations, leading to deficiency in Rab escort protein 1 (REP1)." (PMID 31548516, 2019). "The identification of a pathogenic variant in the CHM gene allows the diagnosis of choroideremia to be confirmed." (PMID 30541579, 2018). "Choroideremia (CHM) is a rare, X-linked recessive retinal dystrophy caused by mutations in the CHM gene." (PMID 29707603, 2018). "The data described here are related to the article entitled “Molecular Genetics Characterization and Homology Modeling of the CHM Gene Mutation: A study on Its Association with Choroideremia”." (PMID 29900297, 2018). "Choroideremia is an X linked inherited disease caused by a deficiency of the Rab escort protein 1 (REP1) encoded by the CHM gene." (PMID 28062428, 2017). "CHM gene defect is a confirmed cause of choroideremia, an X-linked disease leading to progressive vision loss." (PMID 28630650, 2017). "Herein we describe a reliable technique for subretinal gene therapy, which is currently used in clinical trials to treat choroideremia using an adeno-associated viral (AAV) vector encoding the CHM gene." (PMID 28820183, 2017). "Twelve males with clinically-diagnosed choroideremia and confirmed hemizygous mutations in the CHM gene were examined." (PMID 27936069, 2016). "In spite of the large existing spectrum of disease-causing variants in CHM gene, the investigations of Chinese patients with choroideremia are rather limited." (PMID 27739455, 2016). "We also aimed at further correlating CHM variants with phenotypic characteristics and biochemical defects of choroideremia patients." (PMID 27070432, 2016). "Previous studies found that cases of choroideremia had been mostly reported in European and Japanese families, but reported CHM mutations from Chinese families have been limited." (PMID 27739455, 2016). "In patients with choroideremia, diagnoses are confirmed with the identification of mutations in the CHM gene, which is mapped to chromosome Xq21.23." (PMID 27739455, 2016). "For example, two individuals referred with clinical indications of RP were found to have ‘likely pathogenic’ mutations in the CHM gene, a cause of choroideremia." (PMID 27208204, 2016). "We herein describe the phenotype and genotype of members in three Chinese families with choroideremia, and disclose the detection of novel mutations of the CHM gene firstly with the targeted exome sequencing (TES) technology." (PMID 27739455, 2016). "Instead, we identified a novel hemizygous c.1475_1476insCA mutation in the choroideremia-associated gene (CHM)." (PMID 26216097, 2015). "Choroideremia is caused by mutations in the CHM gene localized to the long arm of X-chromosome (Xq21.2)." (PMID 23710333, 2013).
choroideremia (continued). "Progression of retinal pigment epithelial alterations during long-term follow-up in female carriers of choroideremia and report of a novel CHM mutation." (PMID 22025891, 2011). "Choroideremia (CHM) is an X-linked form of retinal degeneration caused by loss of function mutants in REP-1 thereby reducing membrane association." (PMID 21651512, 2011). "Choroideremia (CHM) is an X-linked monogenic disease caused by various mutations in the CHM gene that result in the loss of function of Rab escort protein (REP-1) and cause slow degeneration of the retinal pigment epithelium (RPE), choroid and photoreceptors." (PMID 20027300, 2009). "• Choroideremia, an X-linked disorder, due to mutations in CHM encoding the Rab Escort Protein 1 (REP1) and accounting for about 2% of pigmentary retinopathies." (PMID 17032466, 2006). "Other clinical studies on various IRDs, such as choroideremia caused by mutations in the CHM gene, have reported significant improvements in visual acuity and retinal sensitivity, using AAV2-REP1 administered under the retina, indicating a promising therapeutic path for this condition as well." (PMID 40429522, 2025). "However, in humans, CHM mutations primarily lead to choroideremia, with the most severe clinical symptoms occurring in males." (PMID 40332248, 2025). "Choroideremia is caused by variants in the CHM gene which encodes Rab escort protein 1 (REP-1)." (PMID 39858572, 2024). "Choroideremia is an X-linked choroidopathy caused by pathogenic variants in the CHM gene." (PMID 38025158, 2023). "Choroideremia is clinically characterized by progressive vision loss with the degeneration of choriocapillaris and retinal pigment epithelium, resulting from mutations of the CHM gene." (PMID 35456484, 2022). "Choroideremia is caused predominantly by mutations in the gene CHM, which encodes the protein REP1." (PMID 33435268, 2021). "Moreover, in some patients, it is difficult to differentiate choroideremia from RP, and the detection of CHM gene mutations has noteworthy diagnostic value." (PMID 33781268, 2021). "CHM is the only gene known to be associated with choroideremia." (PMID 32487042, 2020). "Choroideremia is an X-linked chorioretinal dystrophy caused by mutations in the CHM gene." (PMID 33110609, 2020). "So far, variants affecting the CHM gene (OMIM 300390) are the sole known cause for choroideremia." (PMID 32364220, 2020). "Mutation of CHM causes degeneration of choroid and finally choroideremia in human." (PMID 31175290, 2019). "In choroideremia, many nonsense mutations in CHM have been described." (PMID 31466352, 2019). "Choroideremia is caused by mutations in the CHM gene, encoding Rab Escort Protein 1 (REP-1)." (PMID 30541579, 2018). "Notably, this is the first report on the CHM gene variants causing choroideremia in the Polish population." (PMID 30541579, 2018). "Altogether 280 disease-associated variants in the CHM gene including substitutions, small insertions and deletions, large deletions ranging from single exons to whole gene and splice defects have been reported to date in patients with choroideremia." (PMID 30541579, 2018). "Mutations in REP1 cause a disease called choroideremia (CHM), which is an X-linked eye disease." (PMID 28055019, 2017). "Mutations in the CHM gene cause choroideremia in multiple ethnic groups." (PMID 27739455, 2016). "In the present study, we evaluated a multi-technique analysis algorithm to describe the mutational spectrum identified in a large cohort of cases and further correlate CHM variants with phenotypic characteristics and biochemical defects of choroideremia patients." (PMID 27070432, 2016). "Almost all reported cases of choroideremia so far have been attributed to functionally null mutations combined with the slow rate of degeneration and small size of the CHM protein coding sequence, which make gene therapy with adeno-associated viral (AAV) vectors an appealing treatment strategy." (PMID 27739455, 2016).
choroideremia (continued). "At least 147 CHM mutations have been reported in patients with choroideremia." (PMID 26216097, 2015). "CHM gene defects can cause choroideremia, a progressive degeneration of the choroid and retina." (PMID 25126438, 2014). "For instance, we could efficiently detect a novel frameshift mutation in the CHM gene in a male patient with choroideremia." (PMID 23940504, 2013). "Mutation spectrum in the CHM gene of Danish and Swedish choroideremia patients." (PMID 22025891, 2011). "Novel truncating mutations of the CHM gene in Chinese patients with choroideremia." (PMID 22025891, 2011). "Choroideremia (CHM) is a rare X-linked retinal disorder caused by mutations in the CHM gene, leading to progressive vision loss due to degeneration of the choroid, retinal pigment epithelium (RPE), and retina." (PMID 39931243, 2025). "Choroideremia (CHM) is an X-linked chorioretinal dystrophy caused by mutations in the CHM gene, affecting the photoreceptors, retinal pigment epithelium (RPE), and choroid." (PMID 39765914, 2024). "Choroideremia (CHM) is an X-linked recessive chorioretinal dystrophy caused by mutations in CHM, encoding for Rab escort protein 1 (REP1)." (PMID 33755601, 2021). "Choroideremia (CHM) is a X-linked recessive chorioretinal dystrophy due to deficiency of the CHM gene product, i.e., Rab escort protein isoform 1 (REP1)." (PMID 34440285, 2021). "X-linked choroideremia (CHM) is a disease characterized by gradual retinal degeneration caused by loss of the Rab Escort Protein, REP1." (PMID 33201897, 2020). "Moreover, immunoblot analysis was also suggested as an alternative diagnostic method (to Sanger sequencing) to simply confirm the clinical diagnosis of choroideremia due to the fact that almost all CHM variants involve loss of function mutations, resulting in the absence of REP-1." (PMID 30541579, 2018). "Rab escort protein-1 (REP1) is linked to choroideremia (CHM), an X-linked degenerative disorder caused by mutations of the gene encoding REP1 (CHM)." (PMID 28230863, 2017). "Choroideremia (CHM) is an X-linked progressive degeneration of these three layers caused by the loss of function of Rab Escort protein-1 (REP1)." (PMID 23460904, 2013). "Its homolog CHM/REP-1 promotes cervical, lung, and colorectal cancer progression, and its mutation can lead to human choroideremia, ultimately causing choroidal neovascularization." (PMID 40842592, 2025). "Choroideremia is an X-linked chorioretinal dystrophy caused by mutations in CHM, encoding Rab escort protein 1 (REP-1), leading to under-prenylation of Rab GTPases (Rabs)." (PMID 38920696, 2024). "Choroideremia (CHM) (REP1, OMIM #300390: X-linked recessive), an uncommon inherited retinal ailment arising due to mutations in the CHM (RPE1) gene, necessitates a diverse array of imaging indicators for both its diagnosis and treatment." (PMID 38610844, 2024). "Choroideremia (CHM) is an X-linked inherited disorder resulting from mutations in gene CHM." (PMID 38606358, 2024). "In this study, we generated a CHM−/− iPSC-RPE model of choroideremia with isogenic control iPSC-RPE cells for comparison." (PMID 38920696, 2024). "This study investigated two novel splice-altering variants, CHM NM_000390.4:c.941-11T>G and CACNA1F NM_005183.4:c.2576+4_2576+5del implicated in choroideremia and cone dystrophy (COD), respectively, resulting in significant visual loss." (PMID 39858572, 2024). "In this study, two novel VUS, CHM c.941-11T>G and CACNA1F c.2576+4_2576+5del, were investigated to assess their splice-altering potential and association with the IRDs choroideremia and cone dystrophy." (PMID 39858572, 2024). "Fibroblasts harboring a UAG PTC collected from humans suffering from Choroideremia (CHM), an X-linked chorioretin dystrophy due to mutations in the CHM gene coding for REP-1 protein, were treated with PTC414." (PMID 38543100, 2024).